CD7 (CD7 molecule)
Diseases named in the same sentence as CD7 in open-access papers (continued):
Sharing a sentence is not in itself a finding about the gene and the disease.
acute myeloid leukemia (38 papers, 2010 to 2025). Acute myeloid leukemia (AML) is a group of neoplasms arising from precursor cells committed to the myeloid cell-line differentiation. "Meanwhile, approximately 30% of patients with acute myeloid leukemia have high expression of CD7 in their tumor cells." (PMID 39845313, 2024). "Meanwhile, the expression of CD7 is also observed in 30% of acute myeloid leukemia (AML),and plays a critical role in the treatment." (PMID 37215124, 2023). "CD66c and CD7 were the most frequent aberrant markers in B-cell acute lymphoblastic leukemia and acute myeloid leukemia, respectively, and the frequency was higher as compared to the literature." (PMID 36629681, 2023). "Many studies have shown that aberrant CD7 is expressed in acute myeloid leukemia markers at various frequencies, ranging from 3% to 42%." (PMID 35350515, 2022). "We then evaluated the ability to target and kill CD7+ acute myeloid leukaemia cells in vitro and in vivo." (PMID 36517851, 2022). "We chose to measure the CD7 expression levels in the acute myeloid leukaemia cell lines MOLM-13, KG-1a, and K562; CD7-overexpressing K562 (K562-CD7) cells; and the CD7-positive human T-lymphocyte leukaemia cell line CCRF-CEM." (PMID 36517851, 2022). "In our study, aberrant CD7 expression occurred at a high frequency in acute myeloid leukemia." (PMID 35350515, 2022). "Another bsADC model was recently developed for CD7+/CD33+ acute myeloid leukemia (AML)." (PMID 34696218, 2021). "In Acute Myeloid Leukemia with minimal differentiation CD7, CD10 were aberrantly expressed." (PMID 29805426, 2018). "This has been shown in a phase I clinical trial (NCT04538599) for a CD7 CAR T cell therapy for the treatment of T-cell lymphoma and CD7-expressing acute myeloid leukemia (AML)." (PMID 36949949, 2023). "Studies have shown that in acute myeloid leukemia (AML), the positive expression of CD7 is an independent unfavorable prognostic factor for PFS." (PMID 40556671, 2025). "A prominent target antigen for this is the receptor CD7, which is expressed in ∼95% of T-ALL, ∼50% of peripheral T cell lymphomas, as well as 10% of acute myeloid leukemias." (PMID 40589566, 2025). "CD7 is a lymphoid antigen expressed on blasts in approximately 30% of acute myeloid leukemia (AML), and its role in AML remains unclear and depends on subgroup evaluation." (PMID 38577341, 2024). "Aberrant CD7, CD5, cCD79a, and cCD3 were found in 45.8%, 33.3%, 8.3%, and 8.3% of patients with acute myeloid leukemia, respectively." (PMID 36648883, 2023). "CD13 and CD33 were the most frequently expressed aberrant markers in patients with ALL, whereas CD7 and CD19 were the most frequently expressed aberrant markers in patients with acute myeloid leukemia." (PMID 35350515, 2022). "Naturally selected CD7 CAR-T cells represent an effective treatment strategy for relapsed and refractory acute myeloid leukaemia patients in preclinical studies." (PMID 36517851, 2022). "Furthermore, traditional CAR T-cell therapy of acute myeloid leukemia (AML) can target CD33 or CD7, which are expressed on normal hematopoietic stem cells (HSCs) and tumor cells." (PMID 34446084, 2021). "CAR-NK-92 cell-based therapy is currently being evaluated in clinical trials for CD33+ acute myeloid leukemia (AML; NCT02944162) and CD7+ leukemia and lymphoma (NCT02742727)." (PMID 31156651, 2019). "Bone marrow immunophenotypic analyses revealed 23% blasts; positivity for CD34, HLADR and CD33; and negativity for CD7, CD19, CD10, CD117, CD36 and CD15, characterizing acute myeloid leukemia (AML), FAB classification M4." (PMID 28832804, 2018).
acute myeloid leukemia (continued). "K12 CAR-T treatment selectively and specifically eliminated a panel of CD7-positive, but not CD7-negative, cell lines and eliminated acute-T-cell-leukemia-patient-derived and acute myeloid leukemia blasts in an effector-to-target ratio-dependent manner." (PMID 40589566, 2025). "Assessing the aberrant markers in acute myeloid leukemias, the non-acute promyelocytic leukemia group presented expression of CD7 and CD56 as the most frequent ones." (PMID 36629681, 2023). "As a lineage-specific receptor, CD7 is expressed in acute myeloid leukaemia cells and T cells but is not expressed in myeloid cells." (PMID 36517851, 2022). "Previous studies have demonstrated that CD7 is also expressed in over 95% of T-ALL, 30% of acute myeloid leukemia (AML), and some lymphomas." (PMID 38254706, 2024). "Aberrant CD7 and cCD79a expression was present in two cases of acute myeloid leukemia without maturation (AML-M1)." (PMID 40103873, 2025). "In Acute Myeloid Leukemia without Maturation CD5, CD7, TdT were aberrantly expressed." (PMID 29805426, 2018).
T-cell lymphoma (30 papers, 2009 to 2025). "While CD7-CAR-T has primarily been studied in T-ALL, loss of CD7 is relatively common in mature T-cell lymphomas, which may limit this approach in PTCL." (PMID 39456582, 2024). "It validates the feasibility and safety of the sequential CD30/CD7 CAR-T therapy for rare CNS T-cell lymphomas, offering a novel treatment strategy for these conditions." (PMID 40777017, 2025). "The targeting of the antigen CD7 with anti-CD7 CAR-Ts has been evaluated in various clinical trials for T-ALL or T cell lymphoma patients." (PMID 40589566, 2025). "The addition of immunophenotyping, as done in this case, further helps to differentiate CTCL from pseudo-T-cell lymphomas and cutaneous pseudolymphomas, which often lack the characteristic CD4+ predominance and CD7 loss seen in MF." (PMID 41523394, 2025). "The activity of an anti-CD7 mAb-ricin A chain immunotoxin in patients with T-cell lymphomas and leukemia, was evaluated." (PMID 36624522, 2023). "Based on previous phenotypic analysis of patient samples, remaining T cells were identified as CD5+ CD7+ and T-cell lymphoma cells as CD5+ CD7‒." (PMID 35158792, 2022). "CD30 and CD7 have emerged as promising targets for T-cell lymphoma." (PMID 40777017, 2025). "CD7 is positive in a few cases with MS and that may lead to an erroneous diagnosis of T-cell lymphoma." (PMID 39458104, 2024). "In the T-cell lymphoma contingent, the less expressed T-cell markers are CD7 and then CD4." (PMID 36428786, 2022). "CD7 is highly expressed in almost all T-ALL and T cell lymphoma patients, with malignant cells within a patient also being uniformly positive for CD7." (PMID 40589566, 2025). "Taken together, CD7-targeted CAR T cell therapy for T-ALL and T cell lymphoma is safe and has shown promising signs of efficacy." (PMID 40589566, 2025). "A recent study has also proposed the inclusion of TRBC1 in a panel for T-cell lymphoma screening, including CD45, CD4, CD2, CD5, TCRγδ, CD7, CD3 and TRBC1." (PMID 40151427, 2024). "Utilizing this foundational technique, CAR-T trials targeting CD3, CD5, CD7, TRBC1, and CCR4 are ongoing and possess immense potential in the treatment of T-cell lymphomas." (PMID 39456582, 2024). "The potential use of a third generation (CD28 and 4-1BB co-stimulatory domains) CD7-specific uCAR for the treatment of r/r T-ALL and non-Hodgkin’s T-cell lymphoma, was described." (PMID 36624522, 2023). "Investigate the safety and efficacy of CD7 CAR-T cells for patients with relapse/refractory CD7+ T-ALL/T-LBL, NK/T cell lymphoma and determine the pharmacokinetics of CD7 CAR-T cells in patients." (PMID 34912707, 2021). "Recently, two clinical trials using CD7-specific CAR-T cells were launched to assess the safety and efficacy in the patients with CD7+ NK/T cell lymphoma (NCT04004637) and T-NHL (NCT04033302), respectively." (PMID 33292562, 2020). "Similar to the initial biopsy, the tumor cells were positive for LCA and CD4; however, they were negative for the other T cell markers, including CD3 and CD7, ruling out the diagnosis of T-cell lymphoma." (PMID 41159020, 2025). "Similarly to CD5 and CD7 molecules, CD3 was firstly evaluated as a therapeutic target in patients with T-cell lymphoma in studies using immunotoxin-loaded anti-CD3ε mAbs." (PMID 33081391, 2020). "Since MS may express T-cell markers (such as CD43, CD45, CD4, and CD7), immunohistochemical expressions of MPO, lysozyme, and CD68 should be analyzed for their distinction from T-cell lymphomas." (PMID 25805673, 2015). "The CD2, CD3, CD4, CD7 and CD8 are used to determine the T cell lymphoma." (PMID 20062547, 2009). "Most mature T-cell lymphomas in our cohort were CD4-positive and were characterised by abnormal immunophenotypic features, including an altered expression of antigens of the T-cell lineage (e.g., CD2, CD3, CD5, and CD7), and abnormal expression of additional antigens such as CD279 and CD10." (PMID 39796028, 2024).
T-cell lymphoma (continued). "Because the tumor cells were positive for LCA and CD4, T-cell lymphoma was considered in the differential diagnosis; however, the other T-cell markers, including CD3 and CD7, were negative." (PMID 41159020, 2025). "This tumor is a CD30+ T-cell lymphoma that is usually positive for CD2 and CD4 with variable expression of CD5, CD7, and CD8 but it is negative for EBER." (PMID 37958219, 2023). "Anaplastic large cell lymphoma is a CD30+ T-cell lymphoma, usually positive for CD2, CD4, and variable expression of CD5, CD7, and CD8 but negative for B-cell markers." (PMID 37958219, 2023).
T-cell acute lymphoblastic leukemia (24 papers, 1991 to 2026). Acute lymphoblastic leukemia of T-cell origin. "And CD7-specific nanobodies fused to PE38 showed cytotoxic efficacy in CD7-expressing T-cell acute lymphoblastic leukemia in vitro and in a preclinical mouse model in vivo." (PMID 29213270, 2017). "In vitro, the 2-mer immunotoxin was 5.6 times more effective than the 1-mer immunotoxin at inhibiting protein synthesis in the CD7+ human T-cell acute lymphoblastic leukaemia (T-ALL) cell line HSB-2 and was also more effective at inhibiting HSB-2 cell proliferation." (PMID 9083340, 1997). "It is also noteworthy that only markers of myeloid origin were expressed as aberrant phenotype in T-cell ALL (CD13, CD33 and HLA-DR) while common T-cell markers i.e. CD3 and CD7 were aberrantly expressed in 3% cases of B-cell ALL/ TAg+ B-ALL." (PMID 29805426, 2018). "In the context of CAR-T therapies, VHH-based CD7-redirected CAR-Ts (NCT04004637) and CD19/CD20-redirected CAR-Ts (NCT03881761) have entered clinical trials to be assessed for the treatment of certain patients T-cell ALL (T-ALL) and B-cell lymphoma, respectively." (PMID 38066569, 2023). "A high rate and fairly durable remission were achieved in a clinical trial involving subjects with relapsed or refractory T cell acute lymphoblastic leukemia (NCT04689659) with CD7-CAR T, while CD7-negative T cell expansion was observed in the subjects." (PMID 37296654, 2023).
T-cell leukemia (15 papers, 2013 to 2025). A malignant disease of the T-lymphocytes in the bone marrow, thymus, and/or blood. "Thence, the loss of CD7 can affect the expression of T-cells, which has a great impact on T-cell leukemia." (PMID 30781701, 2019).
acute leukemia (11 papers, 2011 to 2025). A clonal (malignant) hematopoietic disorder with an acute onset, affecting the bone marrow and the peripheral blood. "The association of worse prognosis of acute leukemia with aberrant markers is shown by some studies particularly myeloid antigens expression in ALL and CD7 in AML but others have disproved such findings." (PMID 40103873, 2025). "Flow cytometry data indicated that the markers CD34, CD33, CD13, and CD7 were common in SET-CAN/NUP214 positive acute leukemia, including ALL." (PMID 35905214, 2022). "We report a case of acute leukemia CD34+/-HLADR+CD7+CD38+cyCD3- in which a diagnosis of AUL was considered." (PMID 22937302, 2011). "In particular, patient #11944 expressed CD2, CD7 and TdT in 94%, 82% and 26% of cells, respectively, while patient #11945 was also positive for CD3 cytoplasmatic expression, TdT and MPO, with a diagnosis of T/myeloid mixed phenotype acute leukemia (T/M MPAL)." (PMID 31817495, 2019). "Moreover, the minimal expression or complete absence of myeloperoxidase and aberrant CD7 expression, along with the morphology of the blasts, can present a challenging differential diagnosis with mixed phenotype acute leukemia (myeloid/T)." (PMID 29541391, 2018).
mycosis fungoides (8 papers, 2005 to 2025). Classical mycosis fungoides is the most common type of mycosis fungoides (MF), a form of cutaneous T-cell lymphoma, and is characterized by slow progression from patches to more infiltrated plaques and eventually to tumors. "This study explored the prognostic significance of immunohistochemical loss of T-cell antigens—specifically CD2, CD3, CD5, and CD7—in patients diagnosed with early-stage mycosis fungoides (MF)." (PMID 40981343, 2025). "This study aimed to determine whether immunohistochemical loss of T-cell markers CD2, CD3, CD5, and CD7 in patients with early-stage mycosis fungoides is associated with overall survival and progression-free survival." (PMID 40981343, 2025). "The initial biopsy revealed features consistent with plaque-stage mycosis fungoides, characterized by CD4 predominance, CD7 deficiency, and a low Ki-67 index (< 5%)." (PMID 41174711, 2025). "After autologous CAR-T cell therapies, patient 1 with mycosis fungoides achieved PR on day 65, relapsed on day 180 and attained CR followed by 11-fraction radiotherapy; patients 2 and 3 suffered CD7+ relapses on day 103 and 140, respectively." (PMID 37095094, 2023). "Studies conducted by flow cytometry tests on CD4+ T cells population identified a specific phenotype (CD26− or CD7− T cells with bright or dim CD3 or CD4 or bright CD7) that represents the phenotype for diagnosis of Sézary syndrome (SS) and mycosis fungoides and correlates with disease progression." (PMID 35205639, 2022). "All enrolled patients had CD7+ T-cell malignancies including adult T-ALL, T-cell lymphoblastic lymphoma, angioimmunoblastic T-cell lymphoma and mycosis fungoides." (PMID 37095094, 2023). "Similarly, the most common form of cutaneous T-cell lymphoma—mycosis fungoides—is characterized by focal plaques and tumors of poorly controlled malignant CD4+ T cells, in which CD7− status correlates with resistance to Gal1-induced apoptosis." (PMID 29463785, 2018).
Immunodeficiency (7 papers, 2021 to 2025). Failure of the immune system to protect the body adequately from infection, due to the absence or insufficiency of some component process or substance. "Targeting T cell malignancies with universal CD7-targeting chimeric antigen receptor T cells (UCART7) can lead to profound immune deficiency due to loss of normal T and NK cells." (PMID 34423790, 2021). "Recent clinical trials have also demonstrated that the proliferation of CD7− T-cells after CD7+ T-cell depletion in patients may compensate for the immune deficiency due to T-cell absence." (PMID 36517851, 2022). "Patients who had not received allogeneic (allo-) hematopoietic stem cell transplantation (HSCT) before CAR-T therapy would develop pancytopenia and immunodeficiency for a long period after CD7 CAR-T therapy; therefore, allo-HSCT is needed in these patients." (PMID 38481998, 2024). "However, our data reinforces that CD7 is expressed on normal T and NK cells, thus, on-target off-tumor elimination of these adaptive and innate immune cells has the potential to induce immunodeficiency." (PMID 40821791, 2025). "As the results, the mice are protected from CD7-CAR-T cell-induced immunodeficiency." (PMID 36248810, 2022). "Furthermore, CAR-T/NK targeting CD7 will clear CD7-positive normal T/NK cells in vivo, HSCT is usually required after CAR-T therapy; otherwise, the treatment causes severe immunodeficiency and potentially life-threatening infection by pathogenic microorganisms." (PMID 36523990, 2022). "For example, whilst CD7-CAR-T cells are able to target T-ALL, normal CD7+ T cells and NK cells are eliminated as well, leading to immunodeficiency." (PMID 36248810, 2022). "Interestingly, while patients’ normal CD7-positive T cells were depleted, CD7-negative T cells expanded, which may have helped mitigate treatment-related immunodeficiency." (PMID 40699780, 2025).
peripheral T-cell lymphoma (6 papers, 2018 to 2025). "For T cell malignancies, the 40 kDa transmembrane glycoprotein CD7 is a particularly interesting target as it is expressed in ∼95% of T-ALL and ∼50% of peripheral T cell lymphomas." (PMID 40589566, 2025). "The patient was diagnosed at an outside laboratory as having a peripheral T-cell lymphoma, supported by the downregulation of CD5 and CD7 in T-cells." (PMID 30687741, 2018). "An ultrasound-guided biopsy of an omental implant was performed, revealing large atypical lymphoid cells positive for CD3, CD2, and CD4, and negative for CD5, CD7, and CD8, with a Ki-67 proliferation index of 90%, consistent with an aggressive peripheral T-cell lymphoma." (PMID 40761963, 2025).
adult T-cell leukemia/lymphoma (5 papers, 2022 to 2025). A peripheral (mature) T-cell neoplasm linked to the human T-cell leukemia virus type 1 (HTLV-1), adult T-cell leukemia/lymphoma is endemic in several regions of the world, in particular Japan, the Caribbean, and parts of Central Africa. "In adult T-cell leukemia/lymphoma (ATLL), stromal cells extensively express Gal-3, which induces apoptosis by binding to CD7." (PMID 40134029, 2025). "However, CD7 is classically downregulated or absent in some T-cell malignancies such as adult T-cell leukemia/lymphoma (ATL) and Sezary syndrome (SS)." (PMID 37798328, 2023). "Adult T-cell leukemia/lymphoma (ATLL) cells showed typical irregular nuclear contours and were characterized by moderate CD2, CD4, and CD5, loss of surface CD3, CD7, and CD26, and dim-to-negative CD279." (PMID 35299754, 2022). "Here, we found that both adult T-cell leukemia/lymphoma (ATLL) patients and ATLL cells had increased CCR8 expression but did not express CD7." (PMID 35693763, 2022).
T-cell immunodeficiency (5 papers, 2022 to 2024). A broad classification of disorders that affect the cell-mediated aspect of the immune response. "Previous studies have shown that CD7 CAR-T cells cause defects in CD7+ T cells in recipients, but CD7− T-cell subsets appear to replace their function to some extent, thereby alleviating treatment-related T-cell immunodeficiency." (PMID 36517851, 2022). "This study suggests that such an approach could resolve T-cell immunodeficiency caused by CD7-CAR therapy, altogether providing a potential new approach for the development of CD7 CAR." (PMID 36523990, 2022). "This study revealed that while treatment led to the depletion of normal CD7-positive T cells, it expanded CD7-negative T cells, potentially mitigating treatment-associated T-cell immunodeficiency." (PMID 38915099, 2024). "In this study, the patients’ CD7 positive T cells were killed and negative CD7 T cells exhibited normal proliferation, suggesting lower therapy-related T cell immunodeficiency." (PMID 36680011, 2023).
B-cell lymphomas (4 papers, 2013 to 2023). "In the present study, we comprehensively evaluated the expression of T-cell markers (CD2, CD3, CD4, CD5, CD7, and CD8) in 501 B-cell lymphomas, including 225 DLBCLs, by flow cytometry and subsequent immunohistochemistry." (PMID 28380441, 2017). "Therefore, the expression of T-cell markers other than CD5, such as CD2, CD4, CD7, and CD8, has not been broadly investigated in a large case series of B-cell lymphomas." (PMID 28380441, 2017).